MTR (5-methyltetrahydrofolate-homocysteine methyltransferase)
Diseases named in the same sentence as MTR in open-access papers (continued):
Sharing a sentence is not in itself a finding about the gene and the disease.
thyroid tumor (1 paper, 2024). A benign or malignant neoplasm affecting the thyroid gland. "We then performed a bioinformatic analysis with the cBioPortal program in patients with different types of cancer we verified the existence of the genes ITGAV and ITGB3 (mTR) and found that thyroid tumors are the ones with the highest αv and β3 integrin expression." (PMID 39596225, 2024).
cancer (32 papers, 2002 to 2025). A tumor composed of atypical neoplastic, often pleomorphic cells that invade other tissues. "Our study establishes that methionine dependence in cancer cells can be driven by loss of MTR activity due to a functional B12 deficiency." (PMID 40605016, 2025). "Taken together, our results suggest that methionine dependence in cancer cells is due to loss of MTR activity, at least in the cell lines studied." (PMID 40605016, 2025). "Plenty of studies have found that MTR A2756G polymorphism has been linked to various cancer, such as prostate cancer, retinoblastoma and lymphoma." (PMID 30559146, 2019). "MTHFR C677T is linked with increased cancer risk in the context of low folate and methionine synthase (MTR), and therefore a high folate intake would be recommended to women with this polymorphism." (PMID 31505792, 2019). "The variant alleles of the SHMT 1 L474F and MTR D919G polymorphisms have been implicated in increased risk of certain cancers." (PMID 29474406, 2018). "Studies addressing the relationship between MTR gene polymorphisms and risk of various cancers have yielded contradictory results." (PMID 27808252, 2016). "Our knowledge on the association of cancer risk and MTR 2756A > G polymorphism is very limited and inconsistent." (PMID 25840420, 2015). "Methionine synthase is encoded by MTR gene whose polymorphism may affect DNA methylation and thus contribute to cancer development." (PMID 36405587, 2022). "The most crucial genetic predictor of cancer appeared to be MTR 2756 polymorphism-mutations." (PMID 30018733, 2018). "MTR expression is indispensable for cancer cells to initiate tumor growth in mice and can influence their responsiveness to antifolate medications." (PMID 39273288, 2024). "When MTR activity is compromised by defective vitamin B12 binding or availability, it disrupts the folate cycle and hinders the rapid proliferation of cancer cells." (PMID 39273288, 2024). "MTHFR, MTR and MTRR genes play key roles in folate metabolism pathway and were most examined in cancer risk and prognosis." (PMID 33033524, 2020). "Inhibiting MTR could potentially serve as a viable alternative for cancer treatment, prompting a reassessment of drug development efforts." (PMID 39273288, 2024). "Likewise, MTR exhibits widespread expression across human cancer cell lines and tumors." (PMID 39273288, 2024). "Irrespective of cancer status, several SNPs were found to be associated with altered serum folate concentrations, including the D919G SNP in methionine synthase (MTR), the L474F SNP in serine hydroxymethyl transferase 1 (SHMT1) and the V175M SNP in phosphatidyl ethanolamine methyltransferase (PEMT)." (PMID 29474406, 2018). "MTR was recently identified as a cancer susceptibility gene regardless of environmental factors." (PMID 21533266, 2011). "Given that high B12 promotes methionine reversion and that MTR flux appears to be altered in methionine-dependent BJ-RAS cells, we wondered if growth of cancer cells in met–hcys+ condition could be limited by insufficient MTR activity." (PMID 40605016, 2025). "We also identified six predicted SQLE, CCT3, IDI1, GBA, MTR, and NCSTN cancer drug target genes." (PMID 31216110, 2019).
tumor (18 papers, 2006 to 2025). "Concurrently, 1CM-associated genes such as MTHFR and MTR exhibit high expression in breast tissue, participating in oxidative stress and epigenetic regulation, synergistically promoting BC tumor growth alongside the PI3K/Akt signaling pathway." (PMID 41415282, 2025). "Several studies have investigated the association of the MTR variant with the development of neoplasia; however, the results are conflicting." (PMID 28587068, 2017). "Among tumours treated with radiochemotherapy and subsequent resection, MTR variant genotype showed higher histopathological response rate than tumours with MTR wild-type genotype (P=0.0442)." (PMID 16333305, 2006). "Tumours with the MTR wild-type genotype (2756AA) showed a median survival time of 16 months, whereas tumours with an MTR variant genotype (2756AG/2756GG) showed a median survival time of 42 months (P=0.0463)." (PMID 16333305, 2006). "Therefore, more studies for a specific type of digestive system cancer are needed to identify potential tumor-specific effect of MTR polymorphism." (PMID 23613867, 2013). "In line with this assumption, by using a xenograft tumor model, we found that the xenograft tumor growth induced by MTR loss and MTHFD2 overexpression could be abrogated by administering the serine metabolism inhibitor NCT503 (which targets the key serine metabolism enzyme PHGDH46)." (PMID 39039072, 2024). "We further evaluated the impacts of MTHFD2, TYMS, and MTR on tumor cell proliferation under PRKDC overexpression conditions." (PMID 39039072, 2024). "We utilized the CCK-8 assay to investigate how alterations in MTHFD2, TYMS, and MTR affect tumor cell growth." (PMID 39039072, 2024). "Tumours with an MTR variant genotype (2756AG/2756GG) showed complete histopathological regression in 46.2% of cases whereas tumours with the MTR wild-type genotype (2756AA) showed complete regression in 0% of cases." (PMID 16333305, 2006). "Multiple pieces of evidence indicate that the involvement of the enzyme MTR in the folate cycle could be crucial for tumor development by specifically disrupting the production of these vital metabolites." (PMID 39273288, 2024). "However, successful targeting of MTR would necessitate that tumor cells exhibit a greater need for MTR activity compared with other tissues." (PMID 39273288, 2024). "DNA was extracted from pretherapeutic tumour biopsies and was subsequently genotyped for common genetic polymorphisms of three genes (MTHFR C677T, MTR A2756G, TS tandem repeat polymorphism) involved in folate metabolism and potentially in sensitivity to 5-FU-based chemotherapy." (PMID 16333305, 2006). "Thus, it remains unclear whether deliberately reducing MTR expression would inhibit tumor growth in animals." (PMID 39273288, 2024). "The results showed that ANXA5, MMP1, MTR, REN, SCN4A, and SMAD3 were upregulated in HC samples, while HP and ACOX1 were downregulated in tumor tissues." (PMID 38599581, 2024). "For this purpose, we transfected the MTHFD2, TYMS, and MTR overexpression or knockdown vectors into the PRKDC-overexpressing HMCB cell line (PRKDC-OE-HMCB), respectively, and exanimated the tumor cell proliferation rates." (PMID 39039072, 2024). "The methionine synthase MTR converts homocysteine to methionine and plays a dominant role in coupling folate and methionine metabolic cycles in the context of tumor." (PMID 39872059, 2023). "As a result, the overexpression of MTHFD2 or TYMS significantly enhanced the tumor cell proliferation rate, whereas the tumor cell growth promoted by MTHFD2 or TYMS overexpression was decreased by the overexpression of MTR." (PMID 39039072, 2024). "Indeed, we found that the expression of metabolic enzymes MTR, AHCY, and SHMT2 was elevated in tumorspheres compared to adherent tumor cells, which supports the idea that hypoxia is a key factor in altering the pattern of one-carbon metabolism in tumorsphere cells." (PMID 39872059, 2023).
autosomal recessive disease (2 papers, 2020 to 2025). Autosomal recessive form of disease. "As with other autosomal recessive diseases, mutations in MTR are typically found in a compound heterozygous state, which often limits the direct correlation between genotype and disease phenotype, e.g., severity, age of onset, and B12 responsiveness." (PMID 40513947, 2025).
retinopathies (2 papers, 2011 to 2023). "cblG type of inherited disorders of vitamin B12 metabolism due to mutations in MTR gene exhibits a wide spectrum of symptoms, including a retinopathy unresponsive to conventional therapies." (PMID 37798757, 2023).
MTR also shares sentences with these, for which no sentence is quoted: infection (12 papers); cobalamin deficiency (10); autism (7); Stroke (5); cardiovascular disease (4); macrocytic anaemia (4); neuroblastoma (4); neurological disorders (4); Hepatic steatosis (3); megaloblastic anemia (3); schizophrenia (3); alcohol dependence (2); anaemia (2); Autoimmunity (2); cognitive disorders (2); endothelial dysfunction (2); epilepsy (2); malaria (2); neural tube defect (2); neuropathy (2); pancreatic cancer (2); acute leukemia (1); adrenoleukodystrophy (1); alcoholism (1); Allergy (1); Alzheimer disease (1); Anxiety (1); biotinidase deficiency (1); bipolar disorder (1); brain cancer (1).
A further 42 diseases each share a sentence with MTR in 1 paper.